NRAS (NRAS proto-oncogene, GTPase)
Diseases named in the same sentence as NRAS in open-access papers (continued):
Sharing a sentence is not in itself a finding about the gene and the disease.
melanoma (continued). "In summary, these exciting data indicate that targeting ABL1/2 and DDR1 in combination with MEKi may be an effective therapeutic regimen for patients with aggressive NRAS-driven melanomas, who have a poor prognosis and limited therapeutic options." (PMID 36765910, 2023). "We had previously identified p38 as a druggable tumor suppressive gene in NRAS-mutant melanomas." (PMID 36765834, 2023). "In this study, the frequency of BRAF mutation was similar in melanoma (63%) and nevi (65.2%) and the BRAF/NRAS transformed nevi did not have a higher chance of being associated with melanoma than a wild type of nevi." (PMID 36676131, 2023). "The ERK pathway has been reported to activate Rac activity in BRAF- and NRAS-mutant melanoma." (PMID 35625714, 2022). "Along with the KRAS inhibitor sotorasib, the proof-of-concept of tunlametininb as a therapeutic approach towards NRAS mutant melanoma may broaden the once challenging area of RAS mutant cancer." (PMID 36386136, 2022). "In addition, targeted therapy for melanoma is primarily an appropriate treatment based on BRAF and NRAS mutational status." (PMID 36601121, 2022). "As RAF inhibitors have been found to relieve the ERK1/2- dependent feedback inhibition of MAPK signaling, inhibition of MEK1/2 along with B-RAF is considered a promising strategy in the treatment of B-RAF -mutated melanoma and MEK inhibition has proved to be beneficial for NRAS-mutated melanoma." (PMID 35756619, 2022). "Cutaneous melanomas often harbor BRAF mutations (≈50%) and to a lesser degree NRAS mutations (28%)." (PMID 35883768, 2022). "For example, in melanoma, NRAS expression is significantly increased, and miR-145-5p inhibits the activation of Mitogen-Activated Protein Kinase (MAPK) and PI3K/AKT signaling pathways by repressing NRAS, thereby inhibiting melanoma cell proliferation, migration, and invasion." (PMID 35339759, 2022). "In these melanoma cells, PAmCherry-NRas and PAGFP-BRAF could both be localized with ∼20–30 nm, with an effective time resolution of 5 s." (PMID 36304112, 2022). "Interestingly, the antitumor effect of USP14 targeting is applicable to BRAFV600E-, NRAS-, and NF1-mutated melanoma cells and to BRAF/MEK inhibitor-resistant cells." (PMID 35884430, 2022). "Because NRAS Q61K, KRAS G13D, and MEK1 Q56P mutations are associated with BRAF inhibitor resistance in BRAF V600E melanoma, we first tested each A375 model cell line for resistance to the FDA-approved BRAF inhibitor compounds dabrafenib and vemurafenib in 2D tissue culture." (PMID 36358868, 2022). "In addition, amplifications at EGFR, BRAF V600E, NRAS and KRAS loci, mutations of NRAS, KRAS and MAP2K1, and PTEN loss are often observed in resistant lesions of melanoma and CRC patients with treatment of combined RAF targeted therapies 85-87." (PMID 35966590, 2022). "Therefore, we selected melanoma cell lines, which belong to the two molecular subgroups, with B-RAF/NRAS mutation status viz." (PMID 35756619, 2022). "In addition, when applying MutSig2CV to identify significantly mutated genes, both NRAS and BRAF, known melanoma drivers, were found to be significantly mutated." (PMID 35654823, 2022). "Finally, we assessed the effectiveness of UHMK1 depletion in combination with the MEK inhibitor trametinib (tram) in the setting of NRAS mutant melanoma." (PMID 35232962, 2022). "This study found that inhibiting RAF and MEK could effectively control cell growth in NRAS-mutant melanoma cell lines that are dependent on the MAPK pathway." (PMID 35954441, 2022). "Genetically, melanoma has been classified based on driver mutations activating the MAPK signaling pathway as (I) BRAF-mutant (50–60%), (II) RAS-mutant (20–30%), (III) NF1-mutant (10–15%) or (IV) triple (BRAF, NRAS and NF1) wild-type melanoma (~10%)." (PMID 36077603, 2022).
melanoma (continued). "The most important mutated genes contributing to melanoma development comprise BRAF, NRAS, and NF1, all of which may upregulate the MAPK/ERK pathway and promote cell proliferation." (PMID 36143375, 2022). "Neurofibromin 1 (NF1), a tumour suppressor gene encoding a negative regulator of RAS, is the most frequently mutated gene in sun-exposed malignant melanoma, after BRAF and NRAS, being associated with a high risk of metastasis and a high rate of treatment failure." (PMID 35334544, 2022). "NRAS mutant melanoma has been the focus of researchers in both targeted therapy and immunotherapy." (PMID 35967450, 2022). "Additionally, two mutant NRAS-driven melanoma cell lines (Mel-Juso; NRASQ61L/WT, and SK-MEL-2; NRASQ61H/Q61H) demonstrated marked growth reduction following loss of AGO2." (PMID 35923912, 2022). "Moreover, we demonstrate that drug-naive NRAS-mutant melanoma cells are also sensitive to DUSP4 silencing, thus broadening the therapeutic potential of targeting this phosphatase." (PMID 35580987, 2022). "The role of RAF proteins in NRAS-driven melanoma was discussed by Dorard and colleagues." (PMID 36430761, 2022). "Similarly, a recent study of 1764 patients with advanced melanoma from a nationwide registry confirmed the prolonged mPFS and mOS in BRAF-mutant melanoma compared with NRAS-mutant and double wild-type melanoma." (PMID 36428582, 2022). "In this study, we have approached this hypothesis by silencing known negative regulators of the MAPK pathway and evaluating the effects of this perturbation on the survival of BRAF/NRAS-mutant melanoma cells." (PMID 35580987, 2022). "Taken together, their results provide the evidence that the [131I]ICF01012 and MEKi combination can be beneficial for the treatment of the advanced pigmented BRAF-mutant melanoma and that [131I]ICF01012 alone is promising for the treatment of NRAS-mutant melanoma." (PMID 36076924, 2022). "Additionally, the specificity of mutations in melanoma for NRAS compared to HRAS and KRAS is noteworthy, thinking that all three isoforms proceed in GIMM and melanoma-related short-term cultures." (PMID 36551688, 2022). "Belvarafenib is a type II RAF inhibitor and is effective in BRAF V600E‐ and NRAS‐mutant melanoma." (PMID 36254250, 2022). "Retraction: 'Effects of miR-145-5p through NRAS on the cell proliferation, apoptosis, migration, and invasion in melanoma by inhibiting MAPK and PI3K/AKT pathways,' Sha Liu, Guozhen Gao, Dexiong Yan, Xiangjun Chen, Xingwei Yao, Shuzhong Guo, Guirong Li, Yu Zhao, Cancer Medicine." (PMID 36081336, 2022). "Grouping melanomas by BRAF or NRAS status did not indicate that driver mutations play a role in the regulation of the MCUA expression (Fig EV1P and Q)." (PMID 36156348, 2022). "Targeted therapeutic options for NRAS-mutant melanoma are limited." (PMID 36402789, 2022). "Thus, we provide evidence for NRAS-oncogene contributions to metabolic rewiring and a proof-of-principle for the treatment of NRASQ61-mutated melanoma combining metabolic stress (glycolysis inhibitors) and previously approved drugs, such as sorafenib." (PMID 36402789, 2022). "In a subsequent phase I trial, ten patients with NRAS-mutant melanoma, one patient with wild type NRAS melanoma, and eight melanoma patients of unknown NRAS status received both tivantinib and sorafenib." (PMID 35954441, 2022). "Melanomas that arise due to sun exposure are generally dominated by NF1 and NRAS mutations." (PMID 34110110, 2022). "Recent research shows that cell growth in melanomas is also influenced by the NRAS gene." (PMID 34110110, 2022). "NRAS wildtype melanoma accounts for approximately 80% of melanomas." (PMID 35967450, 2022). "Interestingly, we demonstrated a selective effect of LY500307 in melanoma cell lines in terms of cell cycle blockage, apoptosis induction and partial EMT reversion, with particular reference to those expressing ERβ in NRAS-mutated genetic background." (PMID 35371312, 2022).
melanoma (continued). "In order to investigate the role of ADCK2 in melanoma, we checked the endogenous mRNA expression levels of nine melanoma cell lines (BRAF and NRAS WT: MeWo, BRAF-mutated: WM2664, A375, HT144, SkMel28, C32 and NRAS-mutated: SkMel30, SkMel103, SkMel173) and normal human melanocytes (NHM)." (PMID 35205819, 2022). "UVB light cooperated equally with each NRAS mutant to enhance tumor onset and burden, revealing that differences in the melanoma-driving capabilities of each variant are independent of UVB carcinogenesis." (PMID 35672316, 2022). "The use of both MEK and CDK4/6 inhibitors may suppress activated MAP kinase pathway and cell cycle checkpoint dysfunction in NRAS mutant melanoma, increasing antitumoral efficacy, by upregulating activity of the RTK-RAS-RAF and RTK-PI3K-AKT signaling cascade." (PMID 35053435, 2022). "NF1 loss often happens in melanomas lacking mutations in BRAF or NRAS, although in 4% of CM these three mutations can coexist." (PMID 36143375, 2022). "There was no clear relationship between either melanoma stage or BRAF/NRAS mutation status and the presence of TERT promoter variant T349C." (PMID 35494035, 2022). "The MEK/PLK1 inhibitor combination might deserve to be further tested in patients with NRAS-driven melanoma." (PMID 36551302, 2022). "In melanoma, the effect of wild-type NRAS on the tumorigenic potential of mutant NRAS is unclear." (PMID 35672316, 2022). "Furthermore, we demonstrate that the HSPB8-mediated autophagy activation is a crucial event to prevent proliferation and migration of both BRAF- and NRAS-mutant melanoma." (PMID 36400750, 2022). "Approximately 20% of melanoma patients have NRAS-mutant tumors." (PMID 34837846, 2022). "In addition to inhibiting the MAPK pathway with MEK inhibitors, suppression of targets upstream of Ras has also been studied in patients with NRAS-mutant melanoma." (PMID 35954441, 2022). "Similarly, another open label, phase Ib trial focuses on the combination effect of cobimetinib and IN10018 (an adenosine triphosphate–competitive focal adhesion kinase inhibitor) in NRAS-mutant melanoma and metastatic uveal melanoma." (PMID 35954441, 2022). "The results showed that Axl and Akt were highly expressed in NRAS-mutant melanoma cells, and stimulation of Axl expression could reduce the inhibitory effect of Akt inhibitor on melanoma cells." (PMID 35310910, 2022). "This regulation could be achieved through a direct interaction of USP9X with the transcription factor ETS-1, preventing its proteasomal degradation by deubiquitination, and favoring its binding activity on NRAS promoters in melanoma cells." (PMID 35884430, 2022). "The second most common oncogene driving malignant melanoma is NRAS." (PMID 35883768, 2022). "Indeed, it is upregulated by the oncogenic kinases BRAF and NRAS, and its overexpression in melanoma cells promotes proliferation and leads to tumor formation when overexpressing cells are injected in mice." (PMID 36286041, 2022). "Interestingly, in patients with NRAS-mutant melanoma, MEK inhibition in combination with immunotherapy tended to improve survival, but prospective studies are warranted to confirm this." (PMID 35234863, 2022). "NRAS, HRAS and KRAS isoforms are mutated in 15–20%, 2% and 2% of melanomas, respectively." (PMID 36286442, 2022). "Non-CSD melanomas develop typically in younger patients and predominantly carry BRAF mutations, while CSD melanomas have a higher mutation burden, more often contain NF1, NRAS or KIT mutations and affect older people at the distal extremities and head and neck region." (PMID 35328746, 2022). "However, intra-tumor heterogeneity is a well-established biological characteristic of human malignancies, including melanoma, affecting the predictiveness of tissue BRAF/NRAS mutational testing." (PMID 35804825, 2022). "For example, deleterious SNPs in NRAS were analyzed for their role in the progression of retinoblastoma, promotion of lung metastasis, and induction of melanoma." (PMID 36051694, 2022).
melanoma (continued). "Future in vivo analyses may also reveal a mutant-specific impact of wild-type NRAS on melanoma initiation." (PMID 35672316, 2022). "Among melanoma patients, NRAS wildtype patients account for about 80% of all cases." (PMID 35967450, 2022). "Since the observed response was restricted to NRASQ61 mutant melanomas, we investigated whether this effect was NRAS oncogene-dependent." (PMID 36402789, 2022). "Moreover, this expression appeared constitutive and independent of the tumor mutational status, as it was observed in all cell lines tested that presented the most common melanoma-associated mutations, namely BRAF/V600E, NRAS/Q61K and NF1." (PMID 35428910, 2022). "We generate eight conditional, knock-in mouse models and show that rare melanoma mutants (NRAS G12D, G13D, G13R, Q61H, and Q61P) are poor drivers of spontaneous melanoma formation, whereas common melanoma mutants (NRAS Q61R, Q61K, or Q61L) induce rapid tumor onset with high penetrance." (PMID 35672316, 2022). "Our data provide a mechanistic explanation for the selection of NRAS mutants in melanoma." (PMID 35672316, 2022). "In one study, KDs accelerated tumor growth in a BRAF mutant melanoma mouse model, whereas the growth of NRAS mutant and BRAF wild-type melanomas remained unaffected, suggesting that the tumor genetic background might determine KD responsiveness." (PMID 35851093, 2022). "In addition, the most frequent and well-known genetic alterations occurring in melanoma are linked to the BRAF, NRAS, KIT, and NF1 genes." (PMID 36431075, 2022). "NRAS mutation-driven melanomas are more frequently seen in primary tumors developing as nodular melanomas on sun-exposed skin." (PMID 35380338, 2022). "Thus, functional differences among the NRAS oncoproteins, rather than preferential UV carcinogenesis, determines which NRAS mutants occur in human melanoma." (PMID 35672316, 2022). "In fact, a recent whole-genome sequencing analysis conducted in yeast repeatedly exposed to UV identified novel UV mutation signatures induced by the formation of atypical, but highly mutagenic, photoproducts that were present in human skin cancers such as BRAF- and NRAS-mutant melanomas." (PMID 35804995, 2022). "Up to this point, no drugs have been approved to specifically treat melanoma patients with NRAS mutation or amplification." (PMID 35053435, 2022). "In addition toMEK inhibitors, inhibitors of other key proteins of the NRAS signaling pathway also repress the proliferation of melanoma with NRASmut." (PMID 36551302, 2022). "In the context of melanoma, prevalent mutations in BRAF, NRAS, MEK, and KIT oncogenes have already made possible the development of specific targeted therapies directed at the MAPK/ERK pathway, often constitutionally activated in melanoma." (PMID 36143375, 2022). "The idea that NRAS-driven melanoma might be more sensitive to immunotherapy may relate to the slightly higher average number of mutations in these tumors compared to BRAF-driven tumors." (PMID 35234863, 2022). "Though NF1 mutations ordinarily happen in CMs lacking mutations in BRAF or NRAS, nearly 4% of melanomas with mutations in BRAF or NRAS also exhibit NF1 mutations." (PMID 36143375, 2022). "Our findings suggest that limiting NRAS-BRAF interactions could prevent the formation of NRAS-mutant melanoma." (PMID 35672316, 2022). "Notably, 28% of patients with sun damage-related melanoma harbor KIT gene mutations, whereas 10% harbor BRAF mutations and 5% harbor NRAS mutations." (PMID 35356202, 2022). "Furthermore, combined treatment with a new generation pan-RAF inhibitor and trametinib has also resulted in synergistic beneficial effects in NRAS-mutant melanoma cases, which has brought hope to those melanoma cases hitherto orphans of a treatment." (PMID 36358912, 2022). "A previous study indicated that MEKi combined with immune checkpoint inhibitors might enhance survival in patients with NRAS mutant melanoma." (PMID 36551688, 2022).
melanoma (continued). "Here, we establish functional hallmarks of NRAS mutants enriched in human melanoma." (PMID 35672316, 2022). "This limited clinical efficacy may be due to insufficient target inhibition, which might be overcome by combining MEK and ERK inhibitors, a treatment modality that induces better responses than either agent alone in NRAS-mutant melanoma in vitro." (PMID 35234863, 2022). "The MAPK pathway is also activated by NRAS mutations that are frequently found in several tumor types and in 15–20% of melanoma patients but not concomitant with BRAF mutations." (PMID 35495634, 2022). "Indeed, the drivers of most common nevi and malignant melanomas are BRAF and NRAS activating mutations, but these alterations are virtually absent in Spitz neoplasms." (PMID 35457030, 2022). "Mutated CRAF was shown to be a rare driver oncogene overexpressed in BRAF or NRAS melanoma cells." (PMID 34063141, 2021). "Like Pathway 1 to melanoma, dysplastic nevi are associated with activating mutations of BRAF or NRAS; additional mutation of the TERT promoter and, sometimes, hemizygous loss of CDKN2A are involved in the morphological progression to a “classical” (superficial spreading) melanoma in situ." (PMID 34277420, 2021). "Because BRAF and NRAS mutations are uncommon in non-cutaneous melanomas, we can consider that each melanoma subtype depends on a different oncogenetic pathway for its development." (PMID 34209084, 2021). "The NRAS oncogene was first identified in a melanoma cell line in 1984." (PMID 34831002, 2021). "Indeed, in melanoma other oncogenic driver mutations mediate tumorigenesis via activation of MAPK/ERK signaling, including activating NRAS mutations and loss-of function mutations in NF1, a GTPase known to downregulate RAS activity." (PMID 34025662, 2021). "Therefore, we conducted this observational study by collecting information on patients with advanced NRAS mutant melanoma and wild-type patients who received immunotherapy." (PMID 34290710, 2021). "Therefore, we evaluated an additional model which only included NRAS wild type lesions in patients with BRAF-wt melanoma (model 3)." (PMID 33915880, 2021). "Apart from those discussed in this review, these include C-KIT and NRAS among other targets, and a new generation of targeted oncogenic driver inhibitors may promote more precise treatment algorithms in melanoma." (PMID 33810078, 2021). "Silencing of AhR suppressed the growth of NRAS-mutant melanoma cells expressing high levels of AhR." (PMID 33451095, 2021). "However, this combination cannot be used for NRAS-mutant melanoma, and currently NRAS-mutant melanoma is treated with immunotherapy or MEK inhibitors as first-line therapy." (PMID 35187538, 2021). "In our previous publication, we have shown that both BRAF- and NRAS-mutant melanoma cell lines significantly upregulated ERK5 signaling when subjected to MEKi using trametinib, selumetinib, binimetinib or cobimatinib, or ERK1/2 inhibition (ERKi) using GDC-0994." (PMID 34299213, 2021). "The TAK1 inhibitor takinib synergized with trametinib in eradicating NRAS-mutant melanoma cells." (PMID 34063141, 2021). "Additionally, they found that CNS involvement was also more likely for NRAS-mutant melanomas at time of distant disease diagnosis." (PMID 35008286, 2021). "Here, we show that a panel of four NRASQ61 mutant melanoma cell lines had varying sensitivity to trametinib treatment and that the Rho/MRTF pathway was activated in the subset of NRAS mutant melanoma cell lines with high intrinsic resistance to trametinib-mediated cell growth inhibition." (PMID 33921974, 2021). "NRAS mutations usually occur independently of BRAF mutations, but 10–20% of melanomas have point mutations in NRAS codons 12, 13 or 61 that may be mutually exclusive with BRAF mutations." (PMID 34441278, 2021).